TRPV2 (transient receptor potential cation channel subfamily V member 2)
Diseases named in the same sentence as TRPV2 in open-access papers (continued):
Sharing a sentence is not in itself a finding about the gene and the disease.
melanoma (continued). "Indeed, our results show that Xenopus melanophores express multiple and similar TRP channels, including Trpm8,15 Trpa1, Trpv1, Trpv2, and Trpv4, to those detected in mammalian melanocytes and melanoma cells." (PMID 40978134, 2025). "To date, TRPV2 is the only Ca2+‐permeant channel reported as directly participating in paxillin‐rich adhesive structures, revealing a mechanism through which TRPV2 could boost melanoma tumor cell invasiveness." (PMID 36744297, 2023). "The interdependence between TRPV2 and the metastatic phenotype of melanoma tumor cells in vitro and in vivo prompted us to evaluate the clinical significance of TRPV2 expression in human melanoma." (PMID 36744297, 2023). "Hence, by regulating adhesion and motility, the mechanosensitive TRPV2 channel controls melanoma cell invasiveness, highlighting a new therapeutic option for migrastatics in the treatment of metastatic melanoma." (PMID 36744297, 2023). "Using 2D and 3D in vitro models, as well as in vivo models and human tissues, we have established the essential role of the mechanosensitive Ca2+ channel TRPV2 during the metastatic switch of melanoma cells, defining this channel as a promising biomarker and migrastatic target." (PMID 36744297, 2023). "TRPV2-mediated melanoma cell death via channel activation favors the antitumor process." (PMID 37892239, 2023). "Taken together, our results highlight a new role for TRPV2 in regulating advanced melanoma cell motility through the control of the calpain‐mediated mechanical maturation of nascent adhesions, conjointly to cofilin‐1‐induced reorganization of the actin cytoskeleton." (PMID 36744297, 2023). "Consequently, the regulation of TRPV2 permeation would globally impact the resting Ca2+ homeostasis, which has been directly correlated to melanoma aggressiveness." (PMID 36744297, 2023). "Therefore, TRPV2 pharmacological blockade hints as a promising therapeutic option for migrastatics in the treatment of advanced‐stage melanoma." (PMID 36744297, 2023). "In highly invasive metastatic melanoma cells, TRPV2‐mediated Ca2+ influx, potentially induced by mechanical forces, induces the cleavage of talin (and potentially of other substrates) by the Ca2+‐dependent calpains, spatiotemporally regulating cell adhesion dynamics." (PMID 36744297, 2023). "Similarly, in human melanoma biopsies, TRPV2 expression increased together with tumor progression, invasive phenotype, metastatic potential and ultimately a shorter life expectancy." (PMID 36744297, 2023). "Additionally, a similar “anti‐migratory” effect was obtained on WM266.4 cells treated with Tranilast, a pharmacological inhibitor of TRPV2, reinforcing the crucial role of TRPV2‐dependent Ca2+ entry in the migration and invasion potentials of melanoma cells." (PMID 36744297, 2023). "As activation of TRPV2 could inhibit cell viability of A2058 melanoma cells, the function of TRPV2 in A2058 cells requires further investigation." (PMID 30881453, 2019). "Meanwhile, in melanoma A2058 cells, pharmacological activation of TRPV2 with 2-APB could inhibit cell proliferation and promote cell apoptosis as well." (PMID 30881453, 2019). "We, therefore, evaluated whether TRPV2 expression affects either of these hallmarks in melanoma." (PMID 36744297, 2023). "Moreover, activation of TRPV2 could lead to the decline of the viability of melanoma A2058 and A375 cells." (PMID 37439014, 2023). "We, therefore, investigated TRPV2 expression with respect to melanoma invasiveness, by quantifying TRPV2 transcripts along with POU3F2(BRN2) transcription factor mRNAs, a well‐established marker of the melanoma invasive phenotype." (PMID 36744297, 2023). "The Kaplan–Meier analysis showed that five upregulated genes were significantly related to both the OS and DFS of melanoma patients, including TUBB4A, PSEN2, SLC45A2, QPRT, and TRPV2." (PMID 37439014, 2023).
melanoma (continued). "Taken together, here we have demonstrated that TRPV2 and TRPV4 were distributed in human melanoma A2058 and A375 cells as well as melanocytes." (PMID 30881453, 2019). "We found that TRPV2/4, TRPA1, and TRPM8 exhibited ectopic distribution both in melanocytes and melanoma cells." (PMID 30881453, 2019). "TRPV2, therefore, represents a great molecular candidate for mediating a tunable force‐transmitting structural linkage from the cytoskeleton to the TME via adhesion complexes, controlling in fine melanoma cell migration." (PMID 36744297, 2023). "Analysis of this tissue cohort demonstrated that overall, malignant melanomas and lymph node metastasis were extensively expressing TRPV2, while benign nevi exhibited faint or no staining." (PMID 36744297, 2023). "TRPV2 activation also promotes bortezomib-induced cell death in RPMI and U166 melanoma-derived cell lines, suggesting that combinatorial treatments using TRPV2 activators and chemotherapeutics may represent an effective strategy to improve cancer therapy." (PMID 32575381, 2020). "TRPV2 is an ion channel, it’s activation mediated melanoma cell death, which may play a negative role in melanoma development." (PMID 32547879, 2020). "Moreover, activation of TRPV2 and TRPV4 could lead to the decline of cell viability for melanoma A2058 and A375 cells." (PMID 30881453, 2019). "Interestingly, we did not observe any significant difference in the size of the melanospheres formed by the WM266.4 cells, whether expressing TRPV2 or not (unpublished observations), confirming that TRPV2 silencing does not disrupt advanced melanoma cells proliferation or survival potentials." (PMID 36744297, 2023). "Meanwhile, 2-APB, an activator of TRPV2 (also activates TRPV1 and TRPV3 but does not affect TRPV4), clearly attenuated the proliferation of A2058 melanoma cells (IC50 = 150 μM)." (PMID 30881453, 2019). "Taken together, these results indicated that activation of TRPV2 by 2-APB could induce necrosis and apoptosis but does not affect cell cycle for A2058 melanoma cells." (PMID 30881453, 2019).
myeloma (8 papers, 2014 to 2025). "Loss, gain, or mutation of the TRPV2 gene have been reported in hematological tumors, including mantle cell lymphoma, multiple myeloma, Burkitt lymphoma, acute myeloid leukemia, and myelodysplastic syndrome." (PMID 33376561, 2020). "For instance, alteration of the TRPV2 expression level was proven to be a prognostic factor for multiple myeloma cases." (PMID 35140788, 2022). "In multiple myeloma patients, TRPV2 overexpression correlated with bone tissue damage and poor prognosis." (PMID 33376561, 2020). "In this regard, a recent study conducted in our laboratory has reported the presence of two distinct myeloma cell subpopulations in MM patients showing different TRPV2 phenotypes: the CD138+ TRPV2+ and CD138+ TRPV2− MM cells." (PMID 24709905, 2014). "Notably, TRPV2 overexpression correlated with a poor prognosis in MM patients due to enhancement of the interaction between myeloma cells and bone marrow stromal cells by the channel's Ca2+ activity, causing osteoclast-mediated bone destruction." (PMID 33376561, 2020). "TRPV2 overexpression was also evidenced by microarray analysis in multiple myeloma (MM) patients." (PMID 24709905, 2014). "For example, there is emerging evidence that TRPV2 expression may be an independent negative prognostic marker in plasma cell myeloma." (PMID 37240443, 2023).
myocardial infarction (8 papers, 2014 to 2023). Gross necrosis of the myocardium, as a result of interruption of the blood supply to the area, as in coronary thrombosis. "While TRPV2-KO mice had better cardiac function than WT, intravenous administration of WT macrophages in the peritoneal cavity significantly reduced the survival of TRPV2-KO mice after MI in a mouse model of myocardial infarction." (PMID 37404813, 2023). "TRPV2, as a target of miR-202-5p, is highly expressed in acute myocardial infarction tissues, consistent with our study results." (PMID 33763489, 2021). "TRPV2 is also expressed in other cell types, such as macrophages, and in fact, TRPV2 knockout improves heart performance after myocardial infarction due to attenuated activity of peri-infarct macrophages." (PMID 31547577, 2019). "In the current study we sought to assess the potential effects of knock outing TRPV2 on the healing processes following myocardial infarction." (PMID 28481959, 2017). "We have recently shown that the expression of the transient receptor potential vanilloid 2 channel, TRPV2, is upregulated in the peri-infarct zone 3–5 days following an acute myocardial infarction (AMI)." (PMID 28481959, 2017). "TRPV2 is upregulated in the myocardial infarction area, which may be involved in the migration ability of macrophages to hypoxic cardiomyocytes." (PMID 37404813, 2023). "More recently, the overexpression of TRPV2 after myocardial infarction was observed in cardiac tissue of rats, and TRPV2 downregulation in knockout mice was related to a better recovery after myocardial infarction, probably because of an attenuated pro-inflammatory response in these mice." (PMID 30881310, 2019). "This hypothesis may account for the data observed in the immnohistochemical analysis showing that three days post myocardial infarction, TRPV2 is expressed mainly in those macrophages which are closest to the injured cardiomyocytes in the peri-infarct zone." (PMID 25136832, 2014). "By employing a GeneChip array analysis we have demonstrated a clear and specific upregulation of the TRP vanilloid 2 (TRPV2) mRNA in the left ventricles (LV) 3–5 days post-acute myocardial infarction (MI) compared to sham-operated controls, both in rats and in mice." (PMID 25136832, 2014). "Of note, modulation of macrophage TRPV2 channels may prevent and treat myocardial infarction." (PMID 37404813, 2023).
colitis (7 papers, 2017 to 2025). Inflammation of the colon. "Furthermore, in mice with DSS-induced colitis model, higher TRPV2 gene expression was associated with higher degrees of intestinal inflammation." (PMID 32455137, 2020). "In a model of TRPV2-deficient mice, the severity of DSS-induced colitis was lower in macroscopic, microscopic, and immunohistochemical levels in comparison with wild-type animals." (PMID 32455137, 2020). "In TRPV2-knockout mice, colitis was less severe due to the reduced infiltration of macrophages, suggesting that the TRPV2 pathway plays a key role in the development of colitis." (PMID 32823895, 2020). "Recent data in experimental animals implicate TRPV2 in the development of colitis whereas contribution of TRPV4 to intestinal inflammation via chemokine release has been reported." (PMID 29914124, 2018). "The role of TRPV2 in colitis development has been studied using a mouse model of DSS colitis." (PMID 38731999, 2024). "Several reports have linked TRPV2 to inflammation e.g., in rheumatic diseases, experimental colitis and oral inflammation, rather than to thermal sensation." (PMID 30235802, 2018). "However, previous knowledge indicates the possible involvement of TRPV2 in experimental colitis." (PMID 29914124, 2018). "The search terms used were "Transient Receptor Potential Channels", "TRP channels", "TRPV1", "TRPA1", "TRPV4", "TRPV2", "TRPM2", "TRPM3", "TRPM7", "TRPM8", "TRPC3", "colitis", "inflammatory bowel disease", "IBD", "ulcerative colitis", "Crohn Disease"." (PMID 41096659, 2025). "TRPV1 and TRPV2 expression in the distal colon, dorsal root ganglion (DRG) and nodose ganglion (NG) was significantly increased in a rat model of TNBS-induced colitis." (PMID 38731999, 2024). "Further studies are required, including other TRP channels (e.g., TRPM2, TRPM3, TRPM8, TRPV2), which have demonstrated beneficial or negative effects on intestinal inflammation in animal models of colitis, to confirm/refute the severity of these effects in humans." (PMID 38731999, 2024). "However, according to existing data on other TRP channels and the observed effects in animal colitis models, there is a need to study positive/negative events associated with TRPM2, TRPM3, TRPM8, and TRPV2 channels in humans." (PMID 38731999, 2024).
dilated cardiomyopathy (7 papers, 2014 to 2022). Cardiomyopathy which is characterized by dilation and contractile dysfunction of the left and right ventricles. "In this way, the overexpression of TRPV2 was also associated with enlarged hearts in patients with dilated cardiomyopathy." (PMID 30881310, 2019). "TRPV2 functional deletion was associated with a decreased development of fibrosis associated with aging, while TRPV2 upregulation was associated with enlarged hearts, increased fibrosis, and myocardial structural defects in patients with dilated cardiomyopathy." (PMID 30881310, 2019). "The level of TRPV2 expression in cardiomyocytes was 10 times higher than that in other cells, and the activation of TRPV2 channels could cause an increase in intracellular Ca2+ and lead to dilated cardiomyopathy." (PMID 36513971, 2022). "Iwata and colleagues first reported cardiac specific overexpression of TRPV2 and demonstrated that blockade of TRPV2 channels prevented ventricular dilation and fibrosis, ameliorated contractile dysfunction in dilated cardiomyopathy in animal models." (PMID 26865051, 2016). "On the other hand, the inhibition of TRPV2 translocation to the plasma membrane improved myocardial dysfunction, improved survival of mice with dilated cardiomyopathy and slowed the progression of dilated cardiomyopathy." (PMID 31315301, 2019).
triple-negative breast carcinoma (7 papers, 2018 to 2025). An invasive breast carcinoma which is negative for expression of estrogen receptor (ER), progesterone receptor (PR), and human epidermal growth factor receptor 2 (HER2). "In triple-negative breast cancer, TRPV2 expression seems to identify a group of patients with a favorable prognosis." (PMID 37240443, 2023). "A higher recurrence-free survival was associated with greater expression of TRPV2 in triple-negative breast cancer (TNBC) and estrogen receptor β- (ERβ-) negative breast cancer patients who underwent a chemotherapy regimen with doxorubicin." (PMID 33376561, 2020). "High TRPV2 expression or its activation by CBD was associated to enhance drug-uptake with a resulting increase of chemosensitivity and cytotoxic effects on cancer cells in GBM and triple negative breast cancer." (PMID 32751388, 2020). "Considering the aggressive nature of triple negative breast cancer (TNBC) and its limited therapeutic options, we proceeded to elucidate the tumorigenic effect of TRPV2 in vivo by injecting the TNBC cell line MDA-MB-231 cells with control vector, shTRPV2-1, or shTRPV2-2 vector into Balb/c nude mice." (PMID 39334351, 2024). "For instance, in triple-negative breast cancer (TNBC), TRPV2 expression correlates with recurrence-free survival of TNBC patients, opening up the possibility that TRPV2 activation, for example, by cannabidiol, might be beneficial as an adjuvant therapy in TNBC." (PMID 41118703, 2025).
viral infection (6 papers, 2021 to 2025). "Knocking out TRPV2 or inhibiting its channel activity in myeloid cells inhibits viral infection and protects mice from Herpes Simplex Virus type 1 (HSV-1) and Vesicular Stomatitis Virus (VSV)." (PMID 39772141, 2024). "The significant upregulation of TRPV2 expression in DF-1 cells 48 h post-DTMUV infection indicates its potential role in facilitating viral infection during DTMUV entry into avian cells." (PMID 39772141, 2024). "Taken together, these data suggest that LRMDA functions downstream of TRPV2 to promote viral infections." (PMID 36261399, 2022). "Collectively, these data demonstrate that knockout of TRPV2 in myeloid cells leads to resistance to viral infections in mice." (PMID 36261399, 2022). "Knockout of TRPV2 in myeloid cells or inhibition of TRPV2 channel activity suppresses viral infection and protects mice from herpes simplex virus 1 (HSV‐1) and vesicular stomatitis virus (VSV) infection." (PMID 36261399, 2022). "In addition, the viral infection was comparable between Lyz2‐Cre;Trpv2fl/fl BMDCs reconstituted with TRPV2E572Q and those with TRPV2E594/604Q, indicating that the Ca2+ permeability of TRPV2 is essential for viral infection in myeloid cells." (PMID 36261399, 2022). "Considering the essential roles of myeloid cells in defense against viral infection, we next examined whether depletion of TRPV2 in myeloid cells affected cellular antiviral responses." (PMID 36261399, 2022). "Because SKF96365 suppresses the ion channel activity of TRPV2 in BMDCs, we further asked whether the inhibitory effect of SKF96365 on TRPV2 would affect the viral infection of BMDCs." (PMID 36261399, 2022). "We next examined whether the calcium permeability of TRPV2 affected viral infection in myeloid cells." (PMID 36261399, 2022). "Because HSV‐1 infection triggers increase of Ca2+ in the cytosol which facilitates viral infection and TRPV2 channel is a non‐selective ion channel and has relatively high Ca2+ permeability, we next examined whether viral infection increased cytosolic Ca2+ through TRPV2." (PMID 36261399, 2022). "However, whether and how TRPV2 modulates homeostatic and virus‐induced Ca2+ signal in myeloid cells to regulate viral infections are completely unclear." (PMID 36261399, 2022). "In addition, knockout of TRPV2 leads to downregulation of Lrmda in BMDCs and BMDMs, and knockdown of Lrmda significantly downregulates the mobility and tension of cell membrane and inhibits viral infections in Trpv2fl/fl but not LyZ2‐Cre;Trpv2fl/fl BMDCs." (PMID 36261399, 2022). "Reconstitution of TRPV2 but not the Ca2+‐impermeable mutant TRPV2E572Q into LyZ2‐Cre;Trpv2fl/fl bone marrow‐derived dendritic cells (BMDCs) restores viral infection." (PMID 36261399, 2022).
asthma (5 papers, 2015 to 2024). "In most of the cells, TRP channels are expressed, and strong evidence for an essential role in airway function and associated diseases, such as CF, asthma, fibrosis and edema was demonstrated for TRPA1, TRPC6, TRPM2, TRPM5, TRPM7, TRPV2, TRPV4 and TRPV6." (PMID 36139480, 2022). "Bronchospasm and asthma-like symptoms developed in response to the action of cold air and high humidity are associated with the participation of TRPV1, TRPV4, and TRPV2 channels in osmoreception." (PMID 34356881, 2021). "At the same time, patients with asthma exhibited an increased mRNA expression of TRPV2 in lung tissues or cells." (PMID 34356881, 2021). "In PBMCs, the increased expression of TRPV2 was closely correlated with childhood asthma." (PMID 32823895, 2020). "The role of the other subfamilies of TPRV in VILI still needs to be elucidated and might be promising because they are reportedly involved in ovalbumin-induced asthma models (TRPV1, TRPV2, TRPV5), and lung epithelial injury caused by cigarette smoke, LPS, seawater inhalation and wood smoke (TRPV3)." (PMID 39664395, 2024). "Therefore, the development of bronchospasm and asthma-like symptoms in response to the action of hyper- and hypoosmolar exogenous stimuli is mediated by the vanilloid receptors, such as TRPV1, TRPV4, and TRPV2." (PMID 34356881, 2021).